ENSG00000307645 (novel transcript)
Gene: Long non-coding RNA gene on chromosome 2 (88,002,587 to 88,016,780, reverse strand). Ensembl gene ENSG00000307645.
Gene Ontology:
Molecular function: pre-mRNA branch point binding
Biological process: mRNA branch site recognition
Cellular component: U2 snRNP